RN7SL475P (RNA, 7SL, cytoplasmic 475, pseudogene)
Gene: Miscellaneous RNA gene on chromosome 1 (59,974,757 to 59,975,054, reverse strand). Ensembl gene ENSG00000265535.
Homologues: Orthologues: chimpanzee Metazoa_SRP (98% identical), macaque Metazoa_SRP (89% identical). Paralogues in human: RN7SL1 (81% identical), RN7SL3 (80% identical), RN7SL2 (80% identical), RN7SL296P (78% identical), RN7SL566P (78% identical), RN7SL357P (78% identical), RN7SL14P (77% identical), RN7SL336P (77% identical), RN7SL381P (77% identical), RN7SL732P (77% identical), RN7SL655P (77% identical), RN7SL113P (76% identical), and 700 more.